INS (insulin)
Diseases named in the same sentence as INS in open-access papers (continued):
Sharing a sentence is not in itself a finding about the gene and the disease.
neurodegenerative disease (continued). "In several species, intermittent fasting (IF) has been shown to have beneficial effects, including delayed aging, increased lifespan, increased insulin sensitivity, reduced ischemic tissue damage, delayed onset of neurodegenerative disease and improved neuronal repair following injury." (PMID 31998762, 2019). "Herein, we discuss about the uptake and distribution of insulin inside the brain, brain insulin signaling and insulin resistance as well as its relation to neurodegenerative diseases with a special focus on protein O-GlcNAcylation and its potential role in the treatment of AD." (PMID 31143098, 2019). "Thus, this section summarizes and discusses the relationship between insulin signaling and autophagy in each of the neurodegenerative diseases." (PMID 31231176, 2019). "AE, especially F2, deserves further investigation and could be developed as an adjuvant to protect neuron degenerative disease related to Aβ and insulin resistance." (PMID 31237881, 2019). "The molecular mechanisms underlying the relationship between brain insulin dysfunction and neurodegenerative disease are not yet clear." (PMID 29673239, 2018). "Contrary, a recent review article mentioned that adiponectin had several protective functions in the peripheral tissues including insulin sensitizing, anti-inflammatory and anti-oxidative effects that may benefit neurodegenerative diseases." (PMID 29324697, 2018). "Insulin has been described to be involved in memory processes in neurodegenerative diseases." (PMID 28542302, 2017). "Considering that insulin has an effect on a number of metabolites and signalling molecules, it is likely that regulation of its level can influence both the levels of cholesterol and the development of neurodegenerative diseases in the brain." (PMID 28432486, 2017). "However, insulin is a highly attractive therapeutic target in neurodegenerative disease, given its role in improving memory, neuroprotection and neurogenesis, as well as its anti-inflammatory properties." (PMID 30202553, 2016). "Further studies to investigate whether PFJ confers its positive effects on degenerative diseases by modulating components of the insulin-signalling pathway are also warranted." (PMID 27795741, 2016). "Ample number of evidence suggested that alterations in brain insulin metabolism could be one pathological factor for neurodegenerative diseases including AD." (PMID 26136647, 2015). "These encouraging results prompted us to explore whether insulin administration could also benefit other neurodegenerative diseases." (PMID 26658276, 2015). "Knowledge of the specific mechanisms relating insulin dysregulation to neurodegenerative diseases would probably allow the development of drugs that may decelerate neurodegeneration." (PMID 22389813, 2011). "The role of lactate as a glucose‐sparing energy substate may have potential relevance for populations with impaired glucose metabolism, such as individuals with brain injury, neurodegenerative diseases or insulin resistance, where enhanced lactate metabolism may serve as a neuroprotective mechanism." (PMID 41037311, 2025). "Moreover, the downregulation of InsR, failure of InsR to bind insulin, and impairment of the insulin cascade may occur in different neurodegenerative diseases." (PMID 38818523, 2024). "Finally, exercise-enhanced insulin signaling plays a vital role in neurodegenerative diseases." (PMID 38818523, 2024). "Therefore, reducing tau protein hyperphosphorylation by restoring insulin signaling may be a vital preventive measure against neurodegenerative diseases." (PMID 38818523, 2024). "Altogether, our findings support that the use of metformin and other anti-diabetic drugs capable of crossing the BBB might be promising strategies for the prevention and/or treatment of neurodegenerative diseases characterized by dysregulation of insulin signalling in the brain." (PMID 39170185, 2024).
neurodegenerative disease (continued). "However, studies linking autophagy to insulin in neurodegenerative diseases remain limited." (PMID 38818523, 2024). "Therefore, a safe, effective, and economical insulin-sensitizing intervention may be a useful strategy for the prevention and treatment of neurodegenerative diseases." (PMID 38818523, 2024). "Furthermore, numerous studies have demonstrated that exercise can enhance insulin sensitivity, thus suggesting that increasing insulin sensitivity through exercise may prevent and ameliorate neurodegenerative diseases." (PMID 38818523, 2024). "In addition, both hormones have a similar pattern of regulatory effects on neurons and glial cells, exerting antiapoptotic and anti-inflammatory effects, as demonstrated for insulin in the use of INI for the treatment of neurodegenerative diseases, including AD." (PMID 36834685, 2023). "Therefore, the dysregulation of these neurotrophic factors is believed to be associated with neurodegenerative diseases, and abnormal IGF/ insulin levels and insulin-related signaling changes have been observed in neurodegenerative diseases, including PD, AD, HD, and ALS." (PMID 38132161, 2023). "Hsa-miR-29b-3p associated with cognitive function and may be linked with adulthood morbidities in subjects born preterm, possibly through regulation of gene sets related to neurodegenerative diseases and insulin signaling as well as VLDL and triglyceride metabolism." (PMID 33911114, 2021). "However, changes in insulin transmission also lie at the root of many neurodegenerative diseases." (PMID 33080950, 2020). "Cumulatively, these findings suggest insulin/IGF signaling dysfunction contributes to the pathogenesis of aging and neurodegenerative diseases like AD and PDD." (PMID 41278191, 2025). "In fact, insulin is a peptide that promotes bone growth and is considered a key player in the pathophysiology of DISH and other spinal inflammatory and degenerative diseases." (PMID 40444238, 2025). "Dysregulation of the PI3K/AKT/GSK3β signaling pathway provokes brain insulin resistance (BIR), neuroinflammation, and neuronal apoptosis, the hallmarks of PD and other neurodegenerative diseases." (PMID 40474025, 2025). "Recent research has started to unravel the paradox of insulin/IGF signalling having both neuroprotective and neurotoxic actions in healthy aging and degenerative disease." (PMID 38674097, 2024). "Despite disappointing results in a large sample of AD patients, insulin therapy merits further evaluation, with a reliable delivery strategy capable of penetrating the BBB, to alleviate cognitive and motor impairments in neurodegenerative disease." (PMID 36258018, 2023). "Since GSK-3β has a crucial role in metabolism, insulin signaling, protein regulation, and inflammation, GSK-3β inhibition is considered an attractive target for therapeutic intervention in metabolic and neurodegenerative diseases." (PMID 35055183, 2022). "Reduced insulin and insulin-growth-factor signaling (IIS), however, can improve symptoms of neurodegenerative diseases in laboratory model organisms and protect against age-associated decline in neuronal function." (PMID 29579685, 2018). "Despite this, chronically lowered insulin/IGF signaling can improve metabolic, synaptic, and cognitive defects in rodent and Drosophila models of several neurodegenerative diseases, leading to what has become known as the “insulin paradox”." (PMID 28902870, 2017). "Although preliminary, these results show the neuroprotection of insulin targeting DMT1 expression and iron uptake during acidosis-dependent ischemic cell death, consequent to iron overload, as occurs in the pathogenesis of several neurodegenerative diseases." (PMID 39062570, 2024). "SURF4 affects insulin secretion, and reductions in NIPA1 are tied to neurodegenerative diseases." (PMID 38681774, 2023).
neurodegenerative disease (continued). "Due to the paradoxical effects of insulin signalling, the current state of our understanding is insufficient to differentiate clearly between the beneficial vs. negative impact on aging and neurodegenerative diseases of reduced insulin signalling." (PMID 36901787, 2023). "Indeed, PI3K/Akt and ERK1/2, as induced by growth hormones and neurotrophins such as insulin, GLP-1 or BDNF, are well-known survival pathways that are deregulated in neurodegenerative diseases." (PMID 36117625, 2022). "Insulin and IGF-1 ligands have already been tested in neurodegenerative diseases." (PMID 33739284, 2021). "The enriched pathway analysis for 23 differentially expressed EV proteins by Ingenuity pathway analysis were enriched the Insulin Secretion Signaling pathway, IGF-1 Signaling and 14-3-3-mediated signaling, which reported to relate with neurodegenerative diseases, including AD and CTE." (PMID 34527416, 2021). "In this way, this review focuses on the role of insulin signaling/resistance and autophagy in some neurodegenerative diseases, discussing pharmacological and non-pharmacological interventions in these diseases." (PMID 31231176, 2019). "Nonetheless, data from human and animal studies regardless of cell type have shown that dysregulation of insulin function contributes to aging and the development of neurodegenerative diseases." (PMID 30072954, 2018). "Insulin, IGF-1 and IGF-2 polypeptide and receptor genes are expressed in neurons and glial cells throughout the brain, and their highest levels of expression are in structures typically targeted by neurodegenerative diseases." (PMID 22329651, 2012). "In summary, alterations in the insulin and/or IGF-1 signaling pathways may contribute to the development and progression of several neurodegenerative diseases." (PMID 27713238, 2009). "Thus, studies aiming to gain a more sophisticated and incisive understanding of how aging, sex differences, and metabolic and degenerative diseases do and do not perturb the salutary functions of the CNS insulin, and related factors are warranted." (PMID 35798912, 2022). "Insulin is also critical for the nonmetabolic functions in the brain contributing to cognitive function, and, as such, impaired PI3K-AKT insulin signalling in the brain has been implicated in neurodegenerative diseases, including AD." (PMID 36555450, 2022). "However, other mechanisms of impaired insulin signaling cascade such as IRS1 and GSK-3 phosphorylation in the pathogenesis of AD as well as other cellular processes need further investigation for development of more effective therapeutic strategy for this devastating neurodegenerative disease." (PMID 31143098, 2019). "STZ treatment of SH-SY5Y cells thus may be an adequate in vitro model of neurodegenerative diseases, but it is not really established for studying the role of insulin resistance in neuronal death and to examine the effect of protective agents acting mainly by improving insulin signaling." (PMID 31858268, 2020).
heart disease (137 papers, 2006 to 2026). "This stabilization persists throughout the day, providing a more consistent metabolic environment, which not only lowers the risk of heart disease but also improves the insulin sensitivity over time." (PMID 40018272, 2025). "Consumption of oats has been proven to lower blood LDL cholesterol levels and blood pressure, thus reducing the risk of heart disease, as well as reducing blood-sugar and insulin levels." (PMID 30868357, 2019). "The factors associated with non adherence of insulin self administration were feeling better, pt developed heart disease and pt went out of home for long time as." (PMID 28680863, 2017). "In this study The factors associated with non adherence to insulin self administration were feeling better, pt developed heart disease and pt went out of home for long time." (PMID 28680863, 2017). "In stressful situations, prolonged exposure to elevated levels of stress hormones can promote, among other effects, insulin resistance, abdominal fat deposition, increased risk of arterial damage, and heart disease." (PMID 28542485, 2017). "First, drugs to induce insulin sensitization (e.g., metformin) should take priority over drugs that induce insulin secretion (e.g., sulfonylurea), which is associated with a reduction and increase in heart disease risk, respectively." (PMID 26682540, 2015). "In particular, these results suggest that insulin is an important pathogenic mediator and highlight the need to regularly measure insulin when evaluating heart disease risk." (PMID 26682540, 2015). "While, several studies have shown that serum pro insulin, pro insulin/insulin are better predictors of the risk of heart disease compared to insulin concentration." (PMID 23870044, 2013). "Numerous studies have highlighted the beneficial effects of swimming in cold water on the cardiovascular system and heart disease risk factors, including lipid profile, blood pressure, and various hormone levels and improving stress adaptation and insulin concentration." (PMID 38612863, 2024). "Interestingly, except for MAFA that is involved in insulin secretion, all 7 gene products were found to be implicated in both pulmonary and cardiac diseases." (PMID 33308225, 2020). "Multivariate regression analysis identified the factors associated with adherence to insulin self administration: those who stopped taking insulin when they feel better, those who have Heart disease and those taking insulin when they were out of home for long time." (PMID 28680863, 2017). "Regarding the different prognosis observed in T2DM treated by insulin, we could conclude that the insulin therapy may identify a different population of diabetic patients with multifactorial risk factors and an advanced heart disease." (PMID 26636106, 2016). "Of the remaining 13 covariates, 12, including age, use of insulin pump therapy and history of ischaemic heart disease, showed only a small residual confounding, with weighted standardised differences below 0.20." (PMID 40272529, 2025). "Almost half (176/400, 44%) received insulin, and the majority had cardiac disease (231/400, 57.7%) and the DM symptom of elevated blood sugar levels while fasting (365/400, 91.3%)." (PMID 40116715, 2025). "Much of our understanding of the roles of the PPAR isoforms, PPARα, PPARδ and PPARγ are in metabolic regulation, as they play roles in insulin sensitivity, glucose homeostasis and oxidation of fatty acids and cardiac disease." (PMID 40704293, 2025). "These patients were frequently coprescribed with insulin or diuretics and usually had comorbidities such as heart diseases or diabetic complications." (PMID 38327270, 2023). "Another limitation of the booklet is the inclusion of only selected types of FRIDs in the content (i.e., antihypertensives, heart disease medications, hypnotics, psychotropics, opioid analgesics, antihyperglycemic agents, and insulin)." (PMID 36612725, 2022).
heart disease (continued). "Flaxseed is full of antioxidants such as tocopherols, betacarotene, cysteine, and methionine which result in a decrease in blood pressure, heart disease, hepatic and neurological disorders, and increased insulin sensitivity." (PMID 34249256, 2021). "Consistent with the likely complex role of insulin signalling in heart disease, deletion of IRS1 and IRS2 docking proteins in liver results in heart failure in mice, whereas deletion of the same genes in cardiac tissue resulted in smaller ventricular mass." (PMID 34660744, 2021). "Insulin, T3, and Ang II can activate the MAPK signaling pathway in various cell types, such activation is closely associated with cardiac diseases." (PMID 31614708, 2019). "The association between blood lipids and cardiovascular health is highly influenced by systemic insulin sensitivity, and resistance to insulin signaling is known to promote the development of heart disease, in part by altering the blood lipid profile." (PMID 30324108, 2018). "Their results add to the body of evidence that insulin is an important etiological factor in heart disease." (PMID 26682540, 2015). "Such a theory is supported by multiple reports that implicate insulin alone in the etiology of both heart disease and T2DM." (PMID 26682540, 2015). "Based on current data, stringent guidelines or strategies regarding non-insulin antidiabetic pharmacotherapy in T2DM patients with heart disease cannot yet be outlined." (PMID 19619327, 2009). "Reduced insulin sensitivity in non-Hispanic Whites has been associated with increased vascular function impairment and risk of heart disease, while the prevalence of IR in non-Hispanic Blacks is significantly higher than in Whites." (PMID 38404616, 2024). "In cardiac disease, insulin tolerance or resistance is a crucial parameter." (PMID 29311974, 2017). "Second, they identify ceramide as a possible mediator of insulin-related heart disorders." (PMID 26682540, 2015). "The men had higher fasting plasma glucose, serum insulin, HOMA-IR, peak leg strength, as well as a higher prevalence of heart disease compared to women." (PMID 19922671, 2009). "Multivariate analysis identified who stopped taking insulin when they feel better, who have Heart disease and those not taking insulin when they were out of home for long time as independent factors for non adherence of insulin self administration." (PMID 28680863, 2017). "Increased perfusion, improved insulin delivery and cardioprotective features of VEGF-B may be of particular benefit for patients with T2DM and ischaemic heart disease if future clinical and translational researches confirm these effects in humans and VEGF-B proves safe for human use." (PMID 28798193, 2017).